TNF (tumor necrosis factor)
Diseases named in the same sentence as TNF in open-access papers (continued):
Sharing a sentence is not in itself a finding about the gene and the disease.
hemorrhage (continued). "In survivors, mean serum TNF-α at baseline was 77±7 pg/ml, rose in a statistically significant fashion following the initial surgery, and remained elevated up to 75 min post-hemorrhage (with statistically significant changes vs. baseline at 0, 15, 30, 45, 60, and 75 min post-hemorrhage)." (PMID 20027315, 2009). "Thus, TNF-α per se is able to induce a similar hemorrhage in CT26 tumors as i.v.-injected Salmonellae." (PMID 19693266, 2009). "Administering TNF-α and NF-κB inhibitors every 8 hours after IVH (up to 48 hours post-hemorrhage) resulted in reduced CSF production and ventricular enlargement, and decreased NF-κB and AQP1 expression in CPEs compared to the IVH group." (PMID 41270129, 2025). "Patients with haemorrhage-hepatitis syndrome had lower concentrations of IFN-α, IFN-λ2/3, IL-1β and IFN-γ and higher levels of IP-10, IFN-λ1, IL-6, IL-10, TNF-α and GM-CSF." (PMID 37090924, 2023). "The production of TNF-α triggered via the activations of both NF-κB and ERK1/2 pathways in thalamic microglia may mediate the role of the increased Fgr in hemorrhage-induced thalamic pain." (PMID 33055425, 2020). "Thus, the presence of TNF-producing macrophages near blood vessels contributes to DENV protease-induced endothelial cell death and hemorrhage development." (PMID 30409217, 2018). "In contrast, and similarly to Group A, the mean baseline TNF-α value in non-survivors was similar to that of the survivors (88±19 pg/ml), and no statistically significant change occurred either following surgery or during the hemorrhage period." (PMID 20027315, 2009). "In contrast, while the mean baseline TNF-α value in non-survivors was similar to that of the survivors (89±9 pg/ml vs. baseline TNF-α in survivors), no statistically significant change vs. baseline occurred either following surgery or during the hemorrhage period." (PMID 20027315, 2009). "Fgr, a member of the Src-family nonreceptor tyrosine kinases, promotes hemorrhage-induced thalamic pain through both NF-κB and ERK1/2-triggered TNF-α production in thamalic microglia." (PMID 33055425, 2020). "TNFα and VEGF were mildly correlated with hemorrhage size in basal ganglia patients, although non-significantly (r=0.32, p=0.08; r=-0.21, p=0.26, respectively), while Hcy and CAR were significantly correlated with ICH size in basal ganglia patients (r=-0.36, p=0.03; r=0.43, p=0.03, respectively)." (PMID 33585095, 2021).
herpes zoster (40 papers, 2011 to 2026). A common dermal and neurologic disorder caused by reactivation of the varicella-zoster virus that has remained dormant within dorsal root ganglia, often for decades, after the patient's initial exposure to the virus in the form of varicella (chickenpox). "Recent population-based observational research indicated a lower risk of herpes zoster associated with IL-17 and IL-23 inhibitors compared to TNF-α inhibitors." (PMID 38392619, 2024). "Acute herpes zoster is linked to increased levels of pro-inflammatory cytokines, such as IL-1, IL-6, and TNF-α, which are also central to the development of CPPD." (PMID 39553018, 2024). "Regarding IL-17 and IL-23 inhibitors, a recent population-based observational study found a lower risk of herpes zoster associated with them than with TNF-α inhibitors, with hazard ratios of 0.58 and 0.79, respectively." (PMID 38137722, 2023). "The results of our study were consistent with those of previous studies, showing a higher incidence of herpes zoster associated with TNF-α inhibitor use than with the use of IL-17 and IL-23 inhibitors." (PMID 38137722, 2023). "A higher proportion of comorbid PsA in patients treated with TNF-α inhibitors than the other biologics could act as a predisposition to the high incidence of herpes zoster and MACEs." (PMID 38137722, 2023). "Currently, whether TNF inhibitors increase the risk of herpes zoster remains controversial." (PMID 39070789, 2024). "Further, the systemic immunosuppression of anti-TNFα therapies hampers the immunogenicity of these vaccines, and in addition, live vaccine (i.e., herpes zoster) was contraindicated in anti-TNFα-treated patients, as it may cause infection from the vaccine virus strain." (PMID 31194726, 2019). "Among patients receiving TNF- α, monoclonal antibodies, especially IFX, have been significantly associated with an increased risk of herpes zoster." (PMID 41025037, 2025). "Molecular dynamics techniques were used to simulate the stability and flexibility of Coix seed adenosine and herpes zoster TNF genes to evaluate their interaction." (PMID 40428401, 2025). "Studies have shown that the average time between initiation of TNF inhibitor therapy and the occurrence of a herpes zoster event of 8–19 months, with incidence peaking in the first 2 years after initiating biologic therapy." (PMID 39070789, 2024). "Previous research indicates there is an increased incidence of herpes zoster in patients receiving anti-TNF-α treatment for RA (P=0.01)." (PMID 39246920, 2024). "The incidence rate of herpes zoster was the highest in patients treated with TNF-α inhibitors (17.0 per 1000 PY), followed by IL-17, IL-23, and IL-12/23 inhibitors (13.3, 7.8, and 2.7 per 1000 PY, respectively)." (PMID 38137722, 2023). "The EAIR of herpes zoster was the highest in the TNF-α inhibitor group (17.0 per 1000 PY), followed by the IL-17, IL-23, and IL-12/23 inhibitors (13.3, 7.8, and 2.7 per 1000 PY, respectively)." (PMID 38137722, 2023). "Herpes zoster was the most common adverse event and was highly reported in patients treated with TNF-α inhibitors, followed by those treated with IL-17, IL-23, and IL-12/23 inhibitors." (PMID 38137722, 2023). "If herpes zoster develops during treatment with TNF inhibitors or JAK inhibitors, targeted therapy should be paused until viral infection is cleared." (PMID 37485474, 2023). "The published rates of herpes zoster incidence during TCZ treatment are similar to those during treatment with anti-TNF inhibitors." (PMID 27092286, 2016). "However, a subanalysis of the patients treated with TNF-α inhibitors showed a relatively lower incidence of herpes zoster (16.06 vs. 17.86 per 1000 PY) and MACEs (3.95 vs. 7.02 per 1000 PY) in patients with PsA compared with those without PsA." (PMID 38137722, 2023).
herpes zoster (continued). "The fluid in skin blisters and peripheral blood of herpes zoster patients has low levels of the Th1 cytokines interleukin (IL)-2 and tumor necrosis factor-α and high levels of the Th2 cytokines IL-10 and IL-4 compared with the levels of these cytokines in samples from a control group." (PMID 32944021, 2020). "It recognized that TNF inhibitors share common ADEs, possibly due to impaired immune function, such as herpes zoster, and highlighted the need for careful selection of TNFis, especially in patients with concurrent malignancies, where drugs like Infliximab might be used with greater caution." (PMID 39029031, 2024). "While some data suggest that certain live virus vaccines eliciting booster or recall responses may be safe in patients receiving TNF inhibitors (for example, zoster, MMR), extrapolation to live organism neoantigen immunizations cannot be assumed, and additional studies are necessary." (PMID 25587634, 2014). "In OCTAVE Sustain with prior tumor necrosis factor inhibitor failure status, serious infection was reported in one case, opportunistic infection other than herpes zoster was not reported, and herpes zoster was reported in 7 out of 57 cases." (PMID 34768752, 2021). "Although live virus vaccines are not recommended in patients receiving biologics, the incidence of herpes zoster in patients receiving TNF inhibitors was not increased compared with non-biological DMARDs." (PMID 25587634, 2014). "Patients using anti-TNF therapies were less likely to receive zoster vaccine than those who were not using anti-TNF agents (hazard ratio (HR), 0.47; 95% CI, 0.33 to 0.67)." (PMID 22024532, 2011). "Thus, vaccination against herpes zoster is recommended 4 weeks before starting TNF inhibitors or JAK inhibitors but not during treatment." (PMID 37485474, 2023). "However, central nervous system herpes zoster viral infections have rarely been described in patients receiving TNF inhibitors, and, to our knowledge, there are no previous reports of herpes zoster meningitis associated with anti-IL-6 therapy." (PMID 27092286, 2016).
myelodysplastic syndrome (40 papers, 2010 to 2025). A clonal hematopoietic disorder characterized by dysplasia and ineffective hematopoiesis in one or more of the hematopoietic cell lines. "TNF-α has also been implicated in BM diseases such as Fanconi anemia, aplastic anemia or myelodisplasic syndromes (MDS)." (PMID 20126546, 2010). "In fact, excessive TNF-α production is linked with BM failure and myelodysplastic syndrome (MDS)." (PMID 35399522, 2022). "TNF-α is known to induce LIF expression through p38MAPK signaling pathway in bone marrow stromal cells from pediatric patients with myelodysplastic syndrome and neuronal retinal cells." (PMID 26839969, 2016). "Noteworthy, a previous study evaluated serum levels of TNF-α, IL-6, and IL-10, in diagnostic samples obtained from patients with AML or high-risk myelodysplastic syndromes." (PMID 23616009, 2013). "Soluble cytokines such as tumor necrosis factor (TNF), interferons (IFNs), and interleukin 6 (IL6) have been linked to hematologic neoplasms related to aging, including myeloproliferative neoplasms (MPN), myelodysplastic syndromes, and AML33–35." (PMID 37730831, 2023). "TNF inhibits the growth of normal hematopoietic progenitor cells but paradoxically increases the proliferation of neoplastic cells in patients with myeloproliferative neoplasms, myelodysplastic syndrome, and Fanconi anemia." (PMID 36581667, 2022). "Moreover, proinflammatory proteins S100A9 and TNFα suppress EPO expression e.g. in myelodysplastic syndrome." (PMID 34565332, 2021). "Although the exact role of TNF in different hematological diseases remains incompletely understood, elevated levels of TNF were found in patients suffering from myeloid leukemia and myelodysplastic syndromes, Fanconi anemia, Hodgkin’s disease and Non-Hodgkin lymphoma." (PMID 34054827, 2021). "Indeed, IFNγ and TNFα (tumor necrosis factor-alpha) can together activate NF-κB and PD-L1 expression in blasts of myelodysplastic syndromes." (PMID 34503236, 2021). "It has been identified that TNF is elevated in serum of patients with aplastic anemia and myelodysplastic syndromes, suggesting that the hematopoietic repressive activity of TNF may contribute to the cytopenic phenotype of these patients." (PMID 29933410, 2018). "Previous studies have demonstrated that IFN-γ and TNF-α activate NF-κB, which in turn induces B7-H1 expression on myelodysplastic syndrome (MDS) blasts." (PMID 36033440, 2022). "Bone marrow macrophages isolated from myelodysplastic syndrome (MDS) patients release higher levels of TNF-α compared to macrophages from healthy donors." (PMID 24523696, 2014). "It has been documented that patients with myelodysplastic syndrome (MDS) present macrophages with increased levels of TNF-α and hematopoietic progenitors with reduced expression levels of CD49d." (PMID 21655188, 2011). "The efficacy of CD33/CD16 BiKE to induce NK cell function in myelodysplastic syndrome (MDS) cases showed significant NK cell degranulation and IFNγ and TNFα production in MDS patients." (PMID 34827170, 2021). "Similarly, TET2 mutant bone marrow cells from myelodysplastic syndrome (MDS) subjects are resistant to the suppressive effects of TNF-α on colony formation." (PMID 32722135, 2020). "Treatment with CD16 × CD33 BiKE enhances degranulation and tumor necrosis factor (TNF)-α, and interferon (IFN)-γ production against CD33+ myelodysplastic syndrome targets and reverses immunosuppression of NK cells by myeloid-derived suppressive cells." (PMID 33299651, 2020). "Although increased TNF-α has been considered to cause ineffective hematopoiesis in myelodysplastic syndromes (MDS), the mechanisms of TNF-α elevation are not known." (PMID 27513856, 2016). "Due to the absence of Th-2 cytokines, such as IL-4 and IL-5, in a subset of 5q minus myelodysplastic syndrome, proinflammatory Th-1 cytokines such as IFN-γ and TNF-α may be exaggerated in an environment conducive to antigen expression." (PMID 22934211, 2012).
myelodysplastic syndrome (continued). "Chronic inflammation stimulates bone marrow T cells to secrete IFN-γ and TNF-α, driving HSC differentiation into myeloid cells, potentially leading to myelodysplastic syndromes (MDS)." (PMID 41153709, 2025).
non-Hodgkin lymphoma (40 papers, 2003 to 2025). Distinct from Hodgkin lymphoma both morphologically and biologically, non-Hodgkin lymphoma (NHL) is characterized by the absence of Reed-Sternberg cells, can occur at any age, and usually presents as a localized or generalized lymphadenopathy associated with fever and weight loss. "A haplotype comprising single nucleotide polymorphisms in the pro-inflammatory cytokine tumor necrosis factor-alpha (TNF-α) has been linked to an increased risk of non-Hodgkin lymphoma, particularly for DLBCL." (PMID 40076681, 2025). "Higher TNF gene expression levels increase one’s risk of developing various types of cancer, including non-Hodgkin’s lymphoma." (PMID 34063545, 2021). "We also observed enrichment of risk SNPs in binding sites for NfκB and TNF (p<0.0001); variation within these two pathways have also been shown to associate with non-Hodgkin’s lymphoma risk." (PMID 26422229, 2015). "Although infliximab (a monoclonal antibody against TNF-α) has been commonly shown to be effective in AS treatment, long-term follow-up studies demonstrated the association between infliximab therapy and increased risk of non-Hodgkin’s lymphoma." (PMID 33935961, 2020). "One study showed that anti-TNF-α therapy increased the risk of non-Hodgkin’s lymphoma." (PMID 28692671, 2017). "Several studies have reported the association between the TNF-α-308G>A polymorphism and non-Hodgkin lymphomas (NHL) risk, however, results are still inconsistent." (PMID 24857911, 2014). "A promoter polymorphism in the pro-inflammatory cytokine tumor necrosis factor (TNF) (TNF G-308A) is associated with increased non-Hodgkin lymphoma (NHL) risk." (PMID 19390683, 2009). "Further, TNF-α is known to play a role in pathogenesis of non-Hodgkin lymphoma through upregulation of inflammatory and antiapoptotic signals." (PMID 40536814, 2025). "Another difference from non-Hodgkin's lymphoma is that IL-5 (AUC = 0.73) and TNF-α (AUC = 0.74) in CML were also found to be useful in distinguishing bacterial infections in the lungs." (PMID 37114211, 2023). "g., infliximab that targets the tumor necrosis factor (TNF) pathway, are broadly immunosuppressive with major side effects including a higher risk of non-Hodgkin’s lymphoma." (PMID 32547701, 2020). "An insignificantly higher rate of exposure to anti-TNFα agents was found in patients who developed non-Hodgkin's lymphoma." (PMID 20064207, 2010). "Nevertheless, in our nested case control study where we controlled for disease activity and duration we still found a higher proportion of anti-TNFα exposure in patients with incident non-Hodgkin's lymphomas vs matched controls." (PMID 20064207, 2010). "There is now convincing evidence that a promoter polymorphism in the pro-inflammatory cytokine tumor necrosis factor (TNF) (TNF G-308A) is associated with increased risk for non-Hodgkin lymphoma (NHL) and specifically with the NHL subtype, diffuse large B-cell lymphoma (DLBCL)." (PMID 19390683, 2009). "Since the approval of TNFα inhibitors, there have been several reports of non-Hodgkin lymphoma arising in this background." (PMID 18366773, 2008). "However, in non-Hodgkin's lymphoma, IL-2, -4, -5, -12P70, -1β, -17A, -17F, -22, and TNF-α play critical roles in bacterial infections of the lungs." (PMID 37114211, 2023). "Interestingly, a polymorphism in the TNF gene itself, which results in higher plasma levels of TNFα, has been shown to corelate with poor outcomes in a number of hematologic malignancies, including Hodgkin’s and non-Hodgkin’s lymphoma." (PMID 35582273, 2019). "Targeting CFLAR by IRF4 may implicate a role for IRF4 in Fas/TRAIL/TNFα-induced apoptosis in non-Hodgkin lymphomas." (PMID 25207815, 2014). "In OSCC correlates with progression and with relapse in children with B-lineage acute lymphoblastic leukemia (ALL), but not with response to treatment and in patients with non-Hodgkin’s lymphoma and diffuse large B cell lymphoma, TNFα is useful to differentiate risk groups." (PMID 33540543, 2021).
non-Hodgkin lymphoma (continued). "While many recent larger scale investigations of TNF-alpha inhibitors in RA specifically have not shown a consistent association, there may be an increased risk of nonmelanomatous skin cancer and non-Hodgkin lymphoma (particularly follicular lymphoma) in patients older than 65 years." (PMID 40893576, 2025). "Combinatory therapy of CD patients with glucocorticoids, immunomodulators, and TNF inhibitors may be associated with an increased risk of non-Hodgkin's lymphoma, lung, skin, and other types of cancers, although no causative relationship of anti-TNF antibodies and carcinogenesis has been proven." (PMID 25045210, 2014). "In addition, an analysis of the Surveillance, Epidemiology, and End Results (SEER)-Medicare data found that anti-TNF therapy increased the risk of certain cancers in older RA patients, particularly follicular lymphoma and the non-melanoma skin cancer (NMSC) and non-Hodgkin’s lymphoma (NHL) groups." (PMID 39120313, 2024).